ENSG00000276225
Gene: Miscellaneous RNA gene on chromosome 14 (100,894,817 to 100,894,913, forward strand). Ensembl gene ENSG00000276225.
Gene Ontology:
Cellular component: nucleus